BCL2 (BCL2 apoptosis regulator)
Diseases named in the same sentence as BCL2 in open-access papers (continued):
Sharing a sentence is not in itself a finding about the gene and the disease.
lymphoma (continued). "However, activation of Hh signalling has been shown to induce expression of bcl2 gene in mouse keratinocytes, chick spinal cord and to maintain Bcl2 gene expression in the mouse lymphoma cells." (PMID 21042410, 2010). "This oligonucleotide almost completely blocked Bcl-2 protein synthesis in lymphoma cells." (PMID 22649602, 2009). "Furthermore, preirradiation of bcl-2 overexpressing lymphoma cells raises cell death rates after TRAIL receptor stimulation." (PMID 19860913, 2009). "We showed that this could be related to increased expression of anti-apoptotic proteins Bcl-2 and Bcl-xL by the human B lymphomas compared to the murine lymphomas." (PMID 20043832, 2009). "Since previous studies implicated p27 in cell cycle regulation by Bcl-2 and our preliminary studies demonstrate dramatic lymphoid hyperplasia and an increase in thymocyte proliferation in young p27 −/− Lck-Bcl-2 mice, lymphoma formation was examined in these animals." (PMID 18382684, 2008). "Moreover, we recently demonstrated that Bcl-2 suppressed lymphoma formation and chromosomal instability in transgenic mice expressing Bax." (PMID 18382684, 2008). "Therefore, developing targeted therapy to proteins such as Bcl-2 that prevent death of lymphoma cells is advantageous." (PMID 18275607, 2008). "It has been shown that transfection of Bcl-2 into B-cell lines could increase cell viability and decrease apoptosis of lymphoma cells and additionally, confers resistance of these cells to chemotherapeutic drugs." (PMID 18275607, 2008). "One of these compounds – ethyl 2-amino-6-bromo-4-(1-cyano-2-ethoxy-2-oxoethyl)-4H-chromene-3-carboxylate (designated HA14-1) – directly triggered apoptosis in Bcl-2-expressing leukaemia and lymphoma cell lines, and also enhanced the cytotoxicity of the antileukaemia drug cytarabine." (PMID 17311012, 2007). "The consistent finding of the BCL-2 protein in lymphomas with testicular localisation may support the clinical observation that these lymphomas are a separate entity." (PMID 7819053, 1995). "We suggest that the presence of the BCL-2 protein in these lymphomas is related to the differentiation stage of the B-lymphocytes or may play a role in the pathogenesis of these lymphomas." (PMID 7819053, 1995). "Because CD115 marks more specialized monocytic cells than the pan-myeloid marker CD11b, we focused on the CD115-positive subpopulation of TIS control;bcl2 lymphomas, which we hypothesized to reflect a more advanced stage in the B-to-M transition compared to the CD115– fraction." (PMID 40159497, 2025). "In the phase Ib BO42203 trial, the addition of the oral BCL-2 inhibitor venetoclax (Ven) to the Pola-R-CHP regimen was evaluated in treatment-naïve, high-risk BCL-2 IHC-positive DLBCL patients, including those with double-hit and triple-hit lymphomas (DHL/THL)." (PMID 41471096, 2025). "Our study reveals that HIV-associated lymphomas display distinct molecular and clinicopathologic characteristics, including a high rate of EBV infection, a predominant GCB phenotype, and a paradoxical profile of high proliferative activity coupled with low BCL2 expression." (PMID 40496610, 2025). "Thus, venetoclax, as an agent targeting Bcl-2, may offer a novel treatment option for this rare type of lymphoma." (PMID 40666527, 2025). "Furthermore, DLBCL is an aggressive tumor in itself, and poor clinical outcome is increased by overexpression of MYC and BCL2 proteins (double-expressor lymphoma, DEL) and a post-germinal immunohistochemical subtype of DLBCL (non-germinal center B-cell (non-GCB)-DLBCL)." (PMID 38542040, 2024). "Furthermore, they have revealed that the mechanism of BCL2 deregulation may influence lymphoma development, but also TME features and interactions with B cells, suggesting it should be carefully selected to design relevant models." (PMID 38022603, 2023).
lymphoma (continued). "In addition, another study described that SHMT2 and BCL2 cooperated to promote the occurrence of lymphoma through the silencing of epigenetic inhibitors, as the enhancement of SHMT2 metabolic enzyme activity was sufficient to convert normal B cells into B-cell lymphoma." (PMID 36110969, 2022). "However, about half of the DLBCL from the identified the high risk group did not harbor gene rearrangements of MYC and BCL2, suggesting the existence of alternative genetic or epigenetic alterations causing a high-grade lymphoma phenotype." (PMID 35060000, 2022). "A lack of BCL2 protein expression in primary high-grade lymphomas, i.e., BCL2- negative defined as being present in <50% of cells, was associated with a very low venetoclax response (the mean response was 30.3% for BCL2+ and 6.3% for BCL2-negative, p = 0.0371)." (PMID 33670870, 2021). "Similarly, Bcl-2 is also an anti-apoptotic protein that inhibits programmed cell death and is believed to play an important role in cell survival and drug resistance of lymphomas, colorectal cancer, prostate cancer, and other malignancies." (PMID 33738259, 2021). "Hence, eIF4A1 inhibition could be a new and effective treatment for aggressive and MYC+/BCL2+ lymphomas." (PMID 33562682, 2021). "The survival disadvantage of EZB/C3 DLBCLs may be at least partially explained by the fact that the mutational characteristics of double hit (DHIT) lymphomas, an aggressive subtype of DLBCL characterized by MYC and BCL2 translocation, are enriched in this category." (PMID 35071240, 2021). "Follicular lymphomas, which could progress to high-grade lymphoma with DH status, account for 5.3% of lymphomas in Korea, while BCL2 translocations are observed in 3.4% of Korean DLBCL patients, both of which are considerably lower than frequencies observed in Western populations." (PMID 33182440, 2020). "In addition, the Cluster 1 included cases with both Myc and BCL2 overexpression also provided another explanation of poor survival of patients in this group, due to their important role in malignant proliferation of the lymphoma cells." (PMID 32201514, 2020). "Thus, we first detected the expression of Bcl-2 and Bcl-x in all lymphoma cell lines." (PMID 31892356, 2019). "In developing lymphoma cells, this corruption might reflect pre-GC mutations of CREBBP, while in our screen this oncogenic corruption could be provided by the forced expression of BCL2, BCL6, or MYC." (PMID 31586074, 2019). "Thus, it is now clear that neither BCL2-positivity is diagnostic for FL, nor BCL2-negativity excludes this type of lymphoma." (PMID 30931307, 2019). "Loss of Tyk2 did not affect Bcl2 expression levels in these lymphoma cells." (PMID 30131584, 2019). "Although our study has focused on the treatment of DHLs with genomic translocation of MYC and BCL2, the concept of simultaneously targeting multi-driver oncogenes may be extended to other DHLs or triple-hit lymphomas (THLs) with genomic abnormalities in BCL6 oncogene." (PMID 31752970, 2019). "Inhibitors of BCL-2, such as venetoclax and navitoclax, were shown to selectively induce apoptosis in malignant cells and have been extensively investigated as single agents and in combination with other drugs in several malignancies, including acute leukemia, lymphomas, and solid tumors." (PMID 29747654, 2018).
lymphoma (continued). "Similar to Bcl-2 transgenic mice, mice engineered to overexpress Bcl-x renders lymphoid cells resistant to numerous apoptotic stimuli and causes an abnormal accumulation of mature lymphocytes, but not overt lymphoma development." (PMID 30671383, 2018). "However, MYC/BCL6 DHLs or MYC/BCL2/BCL6 “triple-hit” lymphomas can also occur." (PMID 27606052, 2016). "Finally, our results showed that, in mice, RI-BPI could be safely administered concurrently with additional anti-lymphoma drugs such as BCL2-, NAE- and proteasome-inhibitor drugs." (PMID 26657288, 2016). "To test whether up-regulation of BCL2 and BCL-XL might cause lymphoma cells to become especially dependent on these pathways for survival in the absence of BCL6, we knocked down BCL6 in OCI-Ly1 cells as before and treated with the BCL2 and BCL-XL inhibitor ABT-737 250 nM for 72 h." (PMID 26657288, 2016). "Therefore, we presume that FOXP1, like BCL2, may require additional genetic hits to initiate lymphoma." (PMID 24416450, 2014). "However, whether Bcl-2 siRNA combined with miR-15a ODN could enhance MTX-induced apoptosis of lymphoma Raji cells remains unknown." (PMID 23691440, 2013). "Therefore, our study suggested that the combined transfection of Bcl-2 siRNA and miR-15a ODN plus MTX could provide an efficacious therapeutic approach to treat lymphoma that expresses Bcl-2." (PMID 23691440, 2013). "Besides FFPE tissue, we tested metaphase preparations using a typical lymphoma translocation marker, BCL2 FISH split probe, and showed that the signal intensity at 60 minutes hybridization was considerably higher using the EC buffer compared with the traditional formamide buffer." (PMID 22911704, 2012). "Recently, Tucker and colleagues reported that Bcl-2 overexpression leading to maintenance of cyclin D1a expression may occur through p38 mitogen-activated protein kinase (MAPK)-mediated signaling pathways in human lymphoma cell lines." (PMID 21760983, 2011). "In addition to having the constitutively active Lyn activity and constitutive BCR signaling, some lymphomas may have over expression of Bcl-2 anti-apoptotic proteins due to chromosomal translocation of BCL2 gene into the Ig loci." (PMID 20043832, 2009). "However, in contrast to Lck-Bcl-2 mice, p27 deficiency had no affect on the development of lymphoma formation in Lck-Bax38/1 transgenic mice." (PMID 18382684, 2008). "In aggressive lymphomas, alterations in the MYC oncogene and anti‐apoptotic regulators such as MCL1 and BCL2 are frequent promoters of this phenotype." (PMID 41169010, 2026). "In triple-hit lymphoma (THL), the diagnosis is confirmed with the presence of MYC alongside both BCL2 and BCL6 rearrangements." (PMID 40428800, 2025). "In regard to our case, results show a BCL2/BCL6-positive, CD10-faint, CD5/CD23-negative phenotype, suggesting a germinal center-derived lymphoma, likely DLBCL or transformed follicular lymphoma." (PMID 40062071, 2025). "Standard histological examination depends on tissue availability and is currently supplemented with molecular tests, as the status of MYC, BCL2, or BCL6 gene rearrangements is required for proper lymphoma classification." (PMID 39905397, 2025). "Using FISH, 23 patients had a BCL2 rearrangement, 28 BCL6, 11 MYC, and seven presented double/triple-hit lymphomas (7.7%)." (PMID 40166656, 2025). "With respect to molecular docking studies, we used Bcl-2, DHFR, HMG-CoA reductase, and FASN as targets and the three terpenoids with the best cytotoxic and anti-lymphoma activity obtained in in vitro and in vivo studies as ligands." (PMID 40565145, 2025). "Another constituent of GSE under investigation is catechin, which has also been shown to exert antiproliferative and apoptotic effects against murine lymphoma cells LB02 by increasing Bax expression and downregulating Bcl-2 and survivin." (PMID 40843004, 2025).
lymphoma (continued). "These mutation patterns indicated divergent evolution of these different lymphomas from a common lymphoma precursor (CLP) cell population, with the FLs and HGBCL‐MYC/BCL2/BCL6 derived from an intermediate subclone of the CLP cell population." (PMID 41047873, 2025). "The patients were divided into groups that differed in the stage of the disease, localization of the lymphoma, and in terms of rearrangements in the MYC, BCL2, and BCL6 genes." (PMID 38861004, 2025). "Conversely, expressions of VEGF and Bcl-2 correlated positively in the DMBA-lymphoma-induced mice that were left untreated, but expressions of VEGF and Bcl-2 correlated negatively with various modalities when CPL-Micelles was present." (PMID 40126665, 2025). "High-grade B-cell lymphomas with MYC and BCL-2 and/or BCL-6 rearrangements occur in 5% to 10% of DLBCL cases, commonly referred to as double- or triple-hit lymphomas." (PMID 41445799, 2025). "We demonstrated that KAT/3BP exhibits both in vitro and in vivo cytotoxic activity in lymphoma models as a single agent, with efficacy maintained in models harboring secondary resistance to BTK, BCL2, and PI3K inhibitors." (PMID 40563683, 2025). "These immunophenotypic markers help differentiate it from other aggressive lymphomas, such as diffuse large B-cell lymphoma (DLBCL), which often shows a lower Ki-67 index and variable expression of BCL6 and BCL2." (PMID 41180747, 2025). "FISH testing is necessary for all large B-cell lymphomas to assess the presence of double-hit or triple-hit lymphoma (high-grade B-cell lymphoma featuring MYC and BCL2 and/or BCL6 rearrangements)." (PMID 40428800, 2025). "Jerry Adams wrote to Cleary in 1986 to ask for the BCL-2 cDNA, hoping to make transgenic mice that overexpressed BCL-2, to see if they developed lymphoma." (PMID 40204952, 2025). "In lymphoma diagnostics, particularly for DLBCL and HGBCL, a Hi-C-based lymphoma assay enables diagnosis-agnostic detection of gene fusions of IGH::MYC and IGH::BCL2, and rearrangements of MYC, BCL2, and BCL6, in a single assay." (PMID 41010038, 2025). "Overall, the genesis of lymphomas are due to typical chromosomal rearrangements, most frequently in the oncogenes MYC, BCL2, or BCL6." (PMID 40126346, 2025). "Only cells over-expressing both BCL-2 and c-MYC formed colonies in soft agar, and some eventually formed lymphomas when transplanted into mice." (PMID 40204952, 2025). "To avoid confounders in the outcome and biomarker analysis, we first analyzed the outcome of patients with MYC/BCL2 and/or BCL6 double-hit lymphoma (N = 7)." (PMID 40166656, 2025). "While most double-hit lymphomas show positivity for MYC and BCL2 proteins and qualify as double-expresser DLBCL, many double-expresser DLBCL cases do not fall under the DH category." (PMID 40428800, 2025). "The expression rates of BCL-2, BCL-6, C-MYC, and Ki-67 ≥ 80% were particularly high in patients with complex karyotypes, most of whom were double-expressor lymphomas." (PMID 40696688, 2025). "IHC results indicated that the lymphoma cells strongly and diffusely expressed CD10 and BCL-2, with scattered positivity for BCL-6 and CD5, 30% positivity for C-MYC, and negativity for MUM-1." (PMID 40746899, 2025). "The World Health Organization (WHO) classifies DLBCL with MYC and BCL2 rearrangements and the simultaneous occurrence of BCL6 gene rearrangement as double-hit lymphoma (DHL) or triple-hit lymphoma (THL)." (PMID 38381215, 2024).
lymphoma (continued). "WHO-HAEM5 separates DLBCL/HGBCL with MYC and BCL2 rearrangements from the previous entity—HGBCL with MYC and BCL2 and/or BCL6 rearrangements, also known as “double-hit”/“triple-hit” (DH/TH) lymphomas." (PMID 39518937, 2024). "In cases with morphological features intermediate between BL and DLBCL, FISH analysis for MYC, BCL2 and BCL6 rearrangements allows the correct differential diagnosis among BL, DH/TH lymphomas and HGBCL, NOS." (PMID 39684922, 2024). "A GCB PDX model, VFN-D7 DHL with low PTEN protein expression harbours both a BCL2 and MYC translocation, hallmarks of double hit lymphoma and the VFN-D1 KTC PDX model has wildtype PTEN protein levels, a BCL2 amplification and MYC copy number gain." (PMID 39284898, 2024). "In the revised 4th edition of the WHO Classification (2017), these lymphomas were categorized as HGBL with MYC, BCL2, and/or BCL6 rearrangements." (PMID 38914869, 2024). "For instance, Venetoclax (a BCL-2–specific inhibitor) and Navitoclax (inhibitors of BCL-2, BCL-xL, and BCL-W) have shown promise in the treatment of leukemia and lymphoma." (PMID 39916955, 2024). "Analysis of cfDNA levels across LBCL subtypes showed that they were particularly elevated in patients with high-grade lymphoma with rearrangement of MYC and BCL2 (median 518 ng/mL) in comparison with patients with other LBCL subtypes (p < 0.001)." (PMID 38254810, 2024). "Selinexor and eltanexor have also been shown to synergize with the BCL-2 inhibitor venetoclax in double hit lymphoma cell lines and patient-derived xenografts harboring MYC and BCL-2 alterations." (PMID 39749030, 2024). "A German high-grade lymphoma study group performed a post hoc analysis of DLBCL patients, treated in prospective clinical trials, regarding their COO and expression of MYC, BCL2, and BCL6." (PMID 38397877, 2024). "Herein, we report a case of HGBL with MYC, BCL2, BCL6, and CCND1 rearrangements, a so-called quadruple hit lymphoma and describe its molecular and cytogenetic features." (PMID 38914869, 2024). "Recently, the WHO lymphoma classification was updated, and high-grade B-cell lymphoma with MYC and BCL2 gene rearrangements (HGBCL) was designated as its own subtype, with an inferior prognosis compared to DLBCL-NOS." (PMID 38542066, 2024). "For instance, venetoclax is an oral BCL-2 inhibitor that was considered a promising addition to R-CHOP, especially in lymphoma patients with MYC and BCL-2 overexpression." (PMID 39596160, 2024). "The WHO-HAEM5 specifies that DH lymphomas require MYC and BCL2 rearrangements, called DLBCL or HGBCL with MYC and BCL2 rearrangements because those with BCL6 rearrangement have a diverse gene expression signature." (PMID 40949653, 2024). "In the previous 2017 WHO classification (WHO-HAEM4), these lymphomas, known as DH or triple-hit (TH) lymphomas, were placed in a provisional category of high-grade B-cell lymphomas with MYC and BCL2 and/or BCL6 rearrangements (HGBCL-DH/TH)." (PMID 39684922, 2024). "Immunohistochemical results of the transformed lymphomas were as follows: CD10, 24% (8/33); Bcl-6, 50% (17/34); MUM1, 65% (20/31); MYC, 30% (6/20); Bcl-2, 79% (27/34); CD5, 32% (9/28); and Ki67 ≥ 60%, 53% (18/34)." (PMID 39460552, 2024). "The final diagnosis for the patient was double hit-lymphoma - high-grade B-cell lymphoma with MYC and BCL-2 rearrangements, a particularly aggressive form of DLBCL with an abysmal prognosis." (PMID 39449881, 2024). "Most double-hit lymphomas very commonly have an inferior prognosis and are marked by MYC plus BCL2 rearrangement in about three-fourths of the cases." (PMID 39449881, 2024). "Double-hit lymphomas (DHL) can be diagnosed by fluorescent in-situ hybridization (FISH), which would reveal translocations of MYC (8q24) and BCL2 (18q21) or/and BCL6 (3q27) in double-hit or triple-hit lymphomas (THL)." (PMID 39449881, 2024).